CFAP58 (cilia and flagella associated protein 58)
Description:
Has an essential role in the assembly and organization of the sperm flagellar axoneme. Required for the elongation of the primary cilium and sperm flagellar midpiece via modulation of the Notch signaling pathway (By similarity).
Synonyms: C10orf80; CCDC147; FLJ35908; bA554P13.1; SPGF49; bA127L20.4; bA127L20.5
Tractability: Small molecule: a structure with a bound ligand is known. PROTAC: ubiquitination databases record sites on it.
Gene: Protein-coding gene on chromosome 10 (104,353,833 to 104,455,102, forward strand). Ensembl gene ENSG00000120051.
Subcellular location: Cell projection, cilium; Cell projection, cilium, flagellum; Cytoplasm, cytoskeleton, microtubule organizing center, centrosome
Subcellular location (Human Protein Atlas): Principal piece; Calyx
Gene Ontology:
Molecular function: protein binding
Biological process: flagellated sperm motility; protein localization to motile cilium; sperm axoneme assembly; sperm mitochondrial sheath assembly; cilium assembly; Notch signaling pathway; sperm flagellum assembly
Cellular component: extracellular region; sperm flagellum; sperm midpiece; sperm principal piece; centrosome; cytoskeleton; cilium; motile cilium
Genetic constraint (gnomAD): Loss-of-function variants: 80 observed, 106.97 expected, observed/expected ratio (o/e) 0.75, 90% interval 0.62 to 0.9. The upper end of that interval is the gene's LOEUF score, 0.9, which puts it in group 3 of 6, group 1 being the genes least tolerant of losing a copy. Missense variants: 905 observed, 972.16 expected, observed/expected ratio (o/e) 0.93, 90% interval 0.88 to 0.98. Synonymous variants: 338 observed, 351.19 expected, observed/expected ratio (o/e) 0.96, 90% interval 0.88 to 1.05.
Homologues: Orthologues: chimpanzee CFAP58 (99% identical), macaque CFAP58 (98% identical), pig CFAP58 (91% identical), guinea pig CFAP58 (89% identical), rabbit CFAP58 (88% identical), mouse Cfap58 (87% identical), rat Cfap58 (87% identical), tropical clawed frog cfap58 (73% identical), zebrafish cfap58 (63% identical), Drosophila melanogaster CG5882 (24% identical). Paralogues in human: CCDC146 (19% identical).
Diseases named in the same sentence as CFAP58 in open-access papers:
CFAP58 is named in the same sentence as 4 diseases in open-access papers, as found by Europe PMC text mining. Sharing a sentence is not in itself a finding about the gene and the disease. The quoted sentences say what the papers report.
infection (1 paper, 2020). The state of being infected such as from the introduction of a foreign agent such as serum, vaccine, antigenic substance or organism. "After 3 days of infection in the astrocytes, a depletion of Cfap58 cells appeared to grow normally, as observed using phase contrast microscopy (data not shown)." (PMID 31904090, 2020).
CFAP58 also shares sentences with these, for which no sentence is quoted: infertile (1 paper); lung carcinoma (1); male infertility (1).